MC1R (melanocortin 1 receptor)
Diseases named in the same sentence as MC1R in open-access papers (continued):
Sharing a sentence is not in itself a finding about the gene and the disease.
melanoma (continued). "Even though the role of MC1R alleles in phenotypic determination is well known, MC1R can affect melanoma susceptibility through both pigmented and non-pigmented pathways." (PMID 34356093, 2021). "For example, the E318K variant in MITF, combined with MC1R R alleles and other haplotypes in e.g., ASIP, were all at elevated frequencies in people with multiple primary melanomas compared to people with a single primary melanoma." (PMID 33681261, 2021). "A stratified analysis of transmission of the R151C allele from parents to melanoma-positive offspring suggested that the contribution of the MC1R variant to the increased risk is independent of its effect on skin type." (PMID 34356109, 2021). "Thus, MC1R is thought to be associated with a poor prognosis and a potential target for the treatment of melanoma, and many studies have shown that the treatment of melanoma by targeting MC1R achieves good efficacy." (PMID 34698109, 2021). "One sporadic melanoma MITF-E318K carrier resulted wild-type for CDKN2A and MC1R genes and displayed only germline variants of unknown significance in ATM and Fanconi anemia complementation group I (FANCI) genes." (PMID 34573422, 2021). "Inherited variation at MC1R is associated with elevated melanoma risk among non-Hispanic whites (NHWs)." (PMID 34201795, 2021). "Among individuals with darker phenotypes, the MC1R variants are associated with BRAF V600E-mutant melanomas on non-sun-exposed skin." (PMID 34442055, 2021). "A pooled analysis including 3830 melanoma cases and 2619 controls showed that the presence of any MC1R variant had a direct effect on melanoma, conferring a 60% higher risk to carriers versus non-carriers." (PMID 34356109, 2021). "Moreover, it has been reported in scientific literature that germline variants, such as MC1R, CDKN2A, and p16 gene variants are also associated with increased risk of melanoma." (PMID 34195089, 2021). "Other genes that may soon be included in hereditary melanoma testing include ACD (adrenocortical dysplasia protein), MC1R, RB1 (retinoblastoma susceptibility gene), and TERF2IP (telomeric repeat-binding factor 2-interacting protein 1)." (PMID 34440462, 2021). "Accordingly, CDKN2A mutation carriers with MC1R variants had a significant lower median age at melanoma diagnosis than CDKN2A mutation carriers with no MC1R variants (37 years versus 47 years)." (PMID 34356109, 2021). "The potential interaction between inherited genetic variation in the MC1R gene, a primary regulator of skin pigmentation associated with increased risk of melanoma, and MITF-E318K has been reported but not confirmed in all studies." (PMID 34573422, 2021). "Regardless, we observed a high co-occurrence of MC1R variants and high MITF expression in melanoma patients (up to 38% co-occurrence), indicating that a subset of melanoma may be driven by mechanisms similar to those reported for the model presented here." (PMID 32605315, 2020). "In two studies reviewed by Ordóñez, MC1R was present in 100% of the 44 melanomas." (PMID 33339193, 2020). "Notably, MC1R variants have been shown to increase the penetrance of CDKN2A mutations, doubling the risk for melanoma." (PMID 32429485, 2020). "The surface of this nanosystem was functionalized with αMSH (alpha‐melanocyte stimulating hormone), which recognizes a special surface receptor expressed on malignant melanoma cells (melanocortin‐1 receptor, MC1‐R), thereby orienting this system specifically to malignant melanoma cells." (PMID 32100402, 2020). "MC1R is identified as an important factor in preventing melanoma formation." (PMID 32714859, 2020).
melanoma (continued). "Individuals carrying MC1R variants, especially those associated with red hair color, fair skin, and poor tanning ability [red hair color (RHC) variants], have a higher risk of developing melanoma." (PMID 32714859, 2020). "Our findings contribute novel evidence on the association between MC1R variation and pigmentation characteristics in Hispanics who were not selected to participate on the basis of their personal or family history of melanoma (or non-melanoma skin cancers)." (PMID 32350296, 2020). "MC1R genotype affects the probability of developing malignant melanoma, nonmelanoma skin cancer, risk for developing complicated sepsis after trauma and development of Parkinson’s disease in humans." (PMID 33292722, 2020). "Because α-MSH has been shown to stimulate PTEN signaling via MC1R in melanocytes, we delineated whether PTEN upregulation participated in the mechanism underlying MTII-mediated melanoma suppression." (PMID 31968661, 2020). "Finally, by colony formation assay, it was revealed that MC1R antibody neutralization attenuated the MTII-mediated inhibition of anchorage-independent growth in melanoma cells." (PMID 31968661, 2020). "To investigate whether MTII-induced melanoma suppression was through the MC1R-mediated signaling pathway, we exploited antibody neutralization to block the interaction between MTII and MC1R in B16-F10 melanoma cells." (PMID 31968661, 2020). "As transformation occurs in the MC1R-variant Hermes 4C cell line, but not in the WT Hermes 3C cell line, we examined TCGA containing a cohort of 470 melanoma cases of Skin Cutaneous Melanoma (SKCM), for the expression status of MITF in MC1R variant carriers." (PMID 32605315, 2020). "While this association was thought to be driven by the predisposition to fair skin, multiple large studies have shown that the presence of a MC1R variant was associated with development of melanoma, independent of all other risk factors including skin type." (PMID 32429485, 2020). "This increased risk of melanoma was not wholly attributed to the fair skin type associated with this MC1R variant." (PMID 33076392, 2020). "Interestingly, the PI3K-AKT pathway, which is commonly activated in many cancers, including melanoma, seems to be under MITF regulation in Hermes 4C with the MC1R inactive variant background." (PMID 32605315, 2020). "Melanocortin receptor 1 (MC1R) is overexpressed in melanoma and may be a molecular target for imaging and peptide receptor radionuclide therapy." (PMID 31163066, 2019). "Additionally, polymorphisms in the G-protein Coupled Receptor (GPCR) melanocortin-1 receptor gene MC1R, which are associated with fair skin and red hair, are risk factors for melanoma." (PMID 30800712, 2019). "MC1R is also involved in the proliferation of melanoma cells." (PMID 31272482, 2019). "Presence of MC1R variants, together with CDKN2A mutations, significantly increases melanoma risk." (PMID 31717496, 2019). "For example, the melanocortin 1 receptor (MC1R) is overexpressed in many human melanoma cells." (PMID 31272482, 2019). "Beyond pigmentation, MC1R plays additional roles in melanoma development." (PMID 30787281, 2019). "Their study showed that individuals carrying two MC1R variants were at a higher melanoma risk independent of UV-exposure symptoms, compared to subjects with wild-type MC1R." (PMID 30249034, 2018). "Thus our study suggest that finasteride inhibits melanogenesis in melanocyte and melanoma cells by inhibiting MC1R." (PMID 29397551, 2018). "It has been known that the presence of MC1R gene variants results in a higher melanoma risk, which is independent of skin type and hair color." (PMID 30249034, 2018). "This suggests that our peptides will not benefit individuals expressing loss-of-function MC1R, who have increased UV sensitivity and high risk for skin cancer and melanoma." (PMID 30205559, 2018).
melanoma (continued). "Furthermore, common variants in melanocortin 1 receptor (MC1R) and a single variant (p.E318K) in microphthalmia-associated transcription factor (MITF) confer a moderately increased risk of melanoma." (PMID 29774366, 2018). "Millions of individuals stand to benefit from this strategy, particularly those expressing mutations in other skin cancer or melanoma susceptibility genes (e.g., CDKN2A), and those heterozygous for MC1R RHC variants, who represent 50% of the entire white population in the U.S.A.." (PMID 30205559, 2018). "It is unclear whether other common variants that have been associated with melanoma, particularly other pigmentation genes, such as SLC45A2, TYR or TYRP-1, may also exhibit a similar modifying effect CDKN2A penetrance similar to MC1R." (PMID 29774366, 2018). "MC1R is expressed in melanocytes, melanoma cells, macrophages, and brain, as well as in leukocytes, where it may mediate an anti-inflammatory action." (PMID 28714883, 2017). "Without considering MC1R polymorphisms, 85% (85/100) of the melanomas had at least one somatic mutation." (PMID 28356599, 2017). "The PLC/PPARγ axis, inside the MC1R transduction machinery, could represent an element which potentially offers new therapeutic approaches for melanoma." (PMID 29020973, 2017). "In summary, on cell lines expressing a wild type MC1R and responding to αMSH in terms of pigmentation, this study confirmed the hyper-proliferative effect of αMSH in primary cultures of melanocytes and the opposite effect in melanoma cell lines." (PMID 29020973, 2017). "Chromosomes 9 and 16 harbor the known melanoma susceptibility loci, CDKN2A and MC1R, respectively." (PMID 28973033, 2017). "Moreover, MC1R and MITF, other than being moderate-penetrance melanoma susceptibility genes, play an important role in the pigmentation of skin and hairs." (PMID 27776349, 2017). "Recent studies have indicated the cooperation between the PPAR family and the melanocyte-stimulating hormone receptor (MC1R)-microphthalmia-associated transcription factor (MITF) signaling pathway, which resulted in enhanced melanogenesis in melanocytes and melanoma cells." (PMID 29145845, 2017). "For example, it was reported that melanoma patients with germline variants in MC1R tended to acquire BRCA1 mutations more likely than those without genetic variants in MC1R." (PMID 27821817, 2017). "Ultraviolet (UV)-induced DNA damage, loss-of-function mutations in CDKN2A, and inactivating variants of melanocortin 1 receptor gene (MC1R) that are associated with poor tanning ability, as well as red hair all play roles in increased risk of melanoma occurrence." (PMID 28039464, 2017). "MC1R and MITF are considered moderate-risk genes for melanoma susceptibility." (PMID 27776349, 2017). "The recent introduction of routine genotyping for germline MC1R variants and somatic NRAS and BRAF mutations may also help to identify individuals at highest risk of melanoma development in the future." (PMID 28078671, 2017). "The MC1R ED1 allele, associated with melanoma in MeLiM pigs, carries a Leu102Pro polymorphism." (PMID 29081790, 2017). "Our finding that activation of ENDBR enhances repair of DNA photoproducts in melanocytes makes it attractive to harness the ENDBR signaling pathway for a melanoma prevention strategy that can globally benefit high risk individuals, regardless of MC1R genotype." (PMID 27582758, 2016). "Intriguingly, MC1R function might also predict therapeutic response to immune-based anti-melanoma therapies." (PMID 27303435, 2016). "As a potential new target for melanoma therapy, mimetic peptides derived from ASIP may be useful in biased inhibition of pro-melanoma functions of MC1R although only a few variants of ASIP have been examined." (PMID 27028866, 2016). "It is thereby reasonable to speculate that MC1R signaling participates in maintaining levels of eIF-4B protein high enough to support robust melanoma cell growth and division." (PMID 27028866, 2016).
melanoma (continued). "While MC1R is well-known as a normal human melanocyte growth receptor, it has not previously been shown to be an important growth receptor for melanoma." (PMID 27028866, 2016). "In a recent study, MC1R variants were correlated with tumor characteristics suggesting that inherited variation in MC1R may play a role in determining the anatomic site of melanomas and may differ with respect to skin pigmentation phenotype." (PMID 26863566, 2016). "We conclude that MC1R plays an important role in regulating melanoma growth and morphology." (PMID 27028866, 2016). "Our study finds that melanomas from individuals carrying MC1R R variants associated with red hair and freckling have a significantly higher somatic mutational burden than melanomas from individuals with no MC1R R variants." (PMID 27403562, 2016). "Our results suggest inherited variation in MC1R may play an influential role in anatomic site presentation of melanomas and may differ with respect to skin pigmentation phenotype." (PMID 25790105, 2015). "The GEM Study provides well-annotated histopathological data for melanomas and complete sequencing of participant DNA at the MC1R locus, which allows for a comprehensive examination of the associations between variants and histopathological tumor characteristics." (PMID 25790105, 2015). "Direct cross-study comparisons are hindered due in part to a lack of standardized measures and characterization of MC1R risk variants, coupled with differences in categorization of melanoma characteristics (e. g. collapsing of anatomic site presentation)." (PMID 25790105, 2015). "Another study did not replicate a significant MC1R-PD association; however, it also did not replicate the PD-melanoma association and was limited by technical/sequencing difficulty." (PMID 26504519, 2015). "We hypothesize that variation in MC1R influences the occurrence of melanomas that can be distinguished by histology or other tumor characteristics." (PMID 25790105, 2015). "Taken together, studies suggest that pharmacologic induction of cAMP in the skin may represent a potential UV-protective strategy for MC1R-defective individuals who are fair-skinned, sun-sensitive and melanoma prone." (PMID 24838074, 2014). "The major MC1R polymorphisms among human populations are the so-called “red hair colored” (RHC) genotypes that yield a characteristic UV-sensitive and melanoma-prone phenotype, namely propensity for sun burning rather than tanning, fair skin complexion, freckling and red/blonde hair." (PMID 24838074, 2014). "Low penetrant genetic variants for the melanocortin-1 receptor (MC1R) gene are very common in populations of European origin and some of these variants have been associated with a 1.5 to 4-fold increased risk of melanoma." (PMID 24134749, 2013). "The melanocortin system containing endogenous agonists (POMC derived peptides) and agonists (agouti protein and AgRP (agouti-related peptide) as well as five MCR subtypes from (MC1R to MC5R) also regulate energy and glucose homeostasis and melanoma has been linked to increased BMI." (PMID 23796690, 2013). "MC1R, nevi and personal history of non-melanoma skin cancer were identified as the strongest predictors of melanoma risk in our study of early-onset melanoma." (PMID 24134749, 2013). "No study has formally assessed the contribution of MC1R genotype to melanoma risk prediction compared with traditional factors." (PMID 24134749, 2013). "Consistently, a relationship between the MC1R loss-of-function ‘R’ alleles (D84E, R142H, R151C, I155T, R160W, and D294H) and risk of cutaneous basal cell carcinoma (OR 1.37–3.16), SCC (OR 1.99) and melanoma (OR 1.38–4.64) has been shown." (PMID 23555311, 2013). "In the present study we observed effect of the associated variants on chromosome 9p21 independent of MC1R variants on melanoma risk." (PMID 23816148, 2013).
melanoma (continued). "MC1R variants are associated with sun-sensitive phenotypes but the association with melanoma appears to be mediated also through non-pigmentary pathways." (PMID 24134749, 2013). "Finally, using a murine in vivo metastasis model we confirm the involvement of Mc1r in migration and metastasis of melanoma." (PMID 22363655, 2012). "Finally, carriers of MC1R RHC variants have been recently suggested to develop melanomas lacking significant pigmentation as also observed in the hypomelanotic melanomas of our twins." (PMID 22978401, 2012). "Interestingly, several studies have reported that melanocortin stimulating hormone (MSH), a melanogenic ligand of Mc1r, inhibits migration and metastasis of melanoma cells." (PMID 22363655, 2012). "Taken together with the data from in vitro experiments, these results support the hypothesis that Mc1r is required for efficient migration and thereby the metastasis of melanoma cells." (PMID 22363655, 2012). "Inherited MC1R variants are thought to increase melanoma risk as a result of consequent relative lack of eumelanin, but it is postulated that there are additional non-pigmentary effects." (PMID 22325793, 2012). "The V60L variant at MC1R, also quite common in the AJ cohort, has been associated with melanoma in some, but not all, populations." (PMID 22277159, 2012). "We tested this hypothesis by looking at Breslow thickness and overall survival (OS) in 10 melanoma cohorts in relation to MC1R genotype." (PMID 22325793, 2012). "However, the MIA gene promoter has still not been adequately studied as a candidate for the gene therapy of melanoma; almost nothing is known about the potential of the MC1R gene promoter." (PMID 22649681, 2011). "Furthermore, to assess the relevance of α-MSH/MC-1R signaling for the regulation of cytotoxicity in human CD8+ T cells melanoma patients with red hair and fair skin (skin type 1) were included." (PMID 20126537, 2010). "The MC-1R coding sequence is known to be highly polymorphic and associations of certain allelic variants with pigmentation phenotypes and risk factors for melanoma and non-melanoma skin cancer development have been reported frequently." (PMID 20126537, 2010). "In melanoma, patients with germline variations in MC1R have a higher frequency of somatic BRAF mutations in their melanomas than patients without MC1R variants." (PMID 20885788, 2010). "The MC1R variants have been suggested to be associated with red hair, fair skin, and increased risk of both melanoma and non-melanoma skin cancers." (PMID 19828018, 2009). "The MC1R variants were suggested to be associated with red hair, fair skin, and increased risk of both melanoma and non-melanoma skin cancers." (PMID 19799798, 2009). "Understanding of population-specific genetic variation in MC1R and the role it plays not just in skin pigmentation, but sun sensitivity and melanoma risk, has the potential to impact clinical care and public health." (PMID 18402696, 2008). "Sequencing of the MC-1R genomic DNA revealed the HBL melanoma line to be homozygous wild type, the A375-SM line to contain a homozygous polymorphism for Arg151Cys, while the C8161 line was heterozygous for Arg151Cys, with the other allele displaying a wild type sequence." (PMID 14612916, 2003). "Thus, stimulated monocytes or the macrophage line THP-1 showed levels of intracellular MC1R expression which were 50–20% of that found in the five melanomas tested (MFI 8 to 18 for stimulated monocytes vs 40 to 85 for the melanomas)." (PMID 12177778, 2002). "The difference in levels of MC1R expression between melanoma cells and normal melanocytes could be confirmed using short time melanocyte in vitro cultures." (PMID 12177778, 2002). "This extensive analysis of melanocortin 1 receptor tissue distribution may be of relevance not only for melanoma immunology, but also for research on the pathogenicity of inflammatory conditions in the skin and neurologic tissues." (PMID 12177778, 2002).